MAP7D2 (MAP7 domain containing 2)
Description:
Microtubule-stabilizing protein that plays a role in the control of cell motility and neurite outgrowth via direct binding to the microtubule (By similarity). Acts as a critical cofactor for kinesin transport. In the proximal axon, regulates kinesin-1 family members, KIF5A, KIF5B and KIF5C recruitment to microtubules and contributes to kinesin-1-mediated transport in the axons (By similarity).
Synonyms: FLJ14503
Tractability: PROTAC: ubiquitination databases record sites on it; its protein half-life has been measured.
Gene: Protein-coding gene on chromosome X (20,006,713 to 20,117,065, reverse strand). Ensembl gene ENSG00000184368.
Subcellular location: Cytoplasm, cytoskeleton, microtubule organizing center, centrosome; Midbody; Cytoplasm, cytoskeleton; Cell projection, neuron projection; Cell projection, axon
Subcellular location (Human Protein Atlas): Nucleoplasm; Cytosol
Gene Ontology:
Molecular function: protein binding; kinesin binding; microtubule binding; microtubule stabilizing activity
Biological process: axon development; microtubule cytoskeleton organization
Cellular component: centrosome; microtubule; microtubule cytoskeleton; midbody; neuron projection; axon; cytoskeleton
Homologues: Orthologues: chimpanzee MAP7D2 (99% identical), macaque MAP7D2 (97% identical), dog MAP7D2 (77% identical), rabbit MAP7D2 (76% identical), guinea pig MAP7D2 (73% identical), rat Map7d2 (71% identical), mouse Map7d2 (71% identical), pig MAP7D2 (67% identical), tropical clawed frog map7d2 (55% identical), zebrafish map7d2a (36% identical), zebrafish map7d2b (29% identical), Drosophila melanogaster ens (24% identical). Paralogues in human: MAP7 (28% identical), MAP7D1 (27% identical), MAP7D3 (20% identical).
Diseases named in the same sentence as MAP7D2 in open-access papers:
MAP7D2 is named in the same sentence as 13 diseases in open-access papers, as found by Europe PMC text mining. Sharing a sentence is not in itself a finding about the gene and the disease. The quoted sentences say what the papers report.
Alzheimer disease (1 paper, 2023). A progressive, neurodegenerative disease characterized by loss of function and death of nerve cells in several areas of the brain leading to loss of cognitive function such as memory and language. "Moreover, top hub genes in this module were associated with the development of Alzheimer’s disease, including VSNL1, INA, CHN1, NMNAT2, and MAP7D2." (PMID 37284017, 2023).
atherosclerosis (1 paper, 2021). A disease characterized by the build-up of fatty material and calcium deposition in the arterial wall resulting in partial or complete occlusion of the arterial lumen. "The green module had 18 genes significantly and jointly associated with early traits of both osteoporosis (DRToBMC) and atherosclerosis (BIMTavg) in model 1, the most significant (p.adj = 3.3 × 10−14) being MAP7 Domain Containing 2 (MAP7D2)." (PMID 33782480, 2021).
colorectal cancer (1 paper, 2023). A primary or metastatic malignant neoplasm that affects the colon or rectum. "MAP7D2 interacts with the MYH9 protein to protect it from ubiquitin-mediated degradation, subsequently reducing the secretion of HMGB1 to inhibit the infiltration of CD8+ cytotoxic T lymphocytes in microsatellite-stable colorectal cancer." (PMID 37875476, 2023).
Graves disease (1 paper, 2025). Graves' disease is an autoimmune disorder that leads to overactivity of the thyroid gland (hyperthyroidism).It is caused by an abnormal immune system response that causes the thyroid gland to produce too much thyroid hormones. "XIST, PPP1R2C, CALHM6, AL672277.1, TSIX, SHROOM1, ADTRP, JUND, SGK1, CHKA, AO008569.1, MAP7D2, and AIF1 were down-expressed genes in TS compared with both the healthy female and the female patient with Graves’ disease." (PMID 39851522, 2025).
large cell lung carcinoma (1 paper, 2021). "The result from the Hou Lung dataset showed that there were 5.453-fold (p = 1.33E-6) in MAP7D2 mRNA expression in large cell lung carcinoma." (PMID 34660263, 2021).
neuroblastoma (1 paper, 2022). Neuroblastoma (NB) is the most common solid, extracranial childhood tumor. "For this experiment, we used a mouse neuroblastoma cell line, N1-E115, in which the expression of Map7d2 and Map7d1, but not Map7 and Map7d3, was detected by quantitative real-time PCR (RT-qPCR)." (PMID 35470240, 2022). "We also examined the cellular functions of Map7D2 using the N1-E115 mouse neuroblastoma cell line, which expresses both Map7D2 and Map7D1 but not Map7 nor Map7D3." (PMID 35470240, 2022).
tumor (1 paper, 2024). "In both in vitro and in vivo experiments, knocking down MAP7D2 resulted in a notable increase in CD8 CTL infiltration, leading to the inhibition of tumor progression." (PMID 39149512, 2024).
MAP7D2 also shares sentences with these, for which no sentence is quoted: hepatic carcinoma (1 paper); mental illnesses (1); osteoporosis (1); osteosarcoma (1); pancreatic cancers (1); Turner syndrome (1).